ALOX15 (arachidonate 15-lipoxygenase)
Diseases named in the same sentence as ALOX15 in open-access papers (continued):
Sharing a sentence is not in itself a finding about the gene and the disease.
colitis (15 papers, 2018 to 2026). Inflammation of the colon. "We found that Alox15 knock-in mice are strongly protected from the development of inflammatory symptoms in the dextran sodium sulfate colitis model when the loss of body weight was used as major readout parameter." (PMID 40653455, 2025). "Since mammalian ALOX15 orthologs have been implicated in different inflammation models Alox15−/− mice have previously been tested in DSS-induced colitis." (PMID 37498393, 2023). "Conversely, transgenic overexpression of human Alox15 renders mice more susceptible to DSS-induced colitis." (PMID 34733403, 2021). "In a dextran sodium sulfate (DSS) induced colitis model that was restricted to female mice, Alox15−/− mice were robustly protected from colitis and weight loss by a mechanism involving sustained epithelial tight junction protein expression." (PMID 34064822, 2021). "Here, we investigated the temporal regulation and anti-inflammatory actions of ALOX15-derived oxylipins in experimental colitis and macrophages." (PMID 41847922, 2026). "In vivo experiments have recently been shown that functional inactivation of the Alox15 gene improved the colonic barrier function so that Alox15−/− mice were protected in the DSS colitis model." (PMID 40653455, 2025). "Functional humanization of mouse Alox15 protected Alox15 knock-in mice from the development of inflammatory symptoms in the dextran sulfate sodium induced colitis model." (PMID 40653455, 2025). "Transgenic fat1 mice, which are rich in endogenous n-3 PUFAs, are protected in the DSS-induced colitis model but additional systemic inactivation of the Alox15 gene counteracted this protective effect." (PMID 37498393, 2023). "DSS colitis is a frequently employed mouse model of gut inflammation and we have previously reported that systemic inactivation of the Alox15 gene protected female mice from the development of inflammatory symptoms." (PMID 37498393, 2023). "To explore the impact of transgenic expression of human ALOX15 in the mouse DSS-colitis model we administered to the mice 2.5% DSS in the drinking water for five consecutive days." (PMID 37498393, 2023). "In DSS colitis, systemic inactivation of the Alox15 gene (Alox15−/− mice) protected female mice from the development of colitis symptoms and transgenic expression of human ALOX15 under the control of the aP2 promoter deteriorated the outcome of the disease." (PMID 34677413, 2021). "Indeed, we observed lower colon tissue concentrations of Mar-2 in Alox15-KI mice at all time points of the experimental colitis." (PMID 40653455, 2025). "We found that Alox15-KI mice developed less intense inflammatory symptoms in the dextran-sulfate-sodium (DSS) induced colitis model and that this protective effect was paralleled by higher colon tissue concentrations of the specialized pro-resolving mediator (SPM) resolvin D5 in the Alox15-KI mice." (PMID 40653455, 2025). "Since humanization of Alox15 reaction specificity impacts the in vitro biosynthetic capacity of the enzyme for pro-resolving lipoxins we tested the susceptibility of Alox15-KI mice in the DSS colitis model." (PMID 40653455, 2025). "However, in a dextran sodium sulfate colitis model, overexpression of ALOX15 hardly impacted the severity of inflammatory indicators even though systematic blocking of the gene did protect female mice from colitis induced by dextran sodium sulfate." (PMID 38612771, 2024). "However, in the dextran sodium sulfate colitis model, in which systemic inactivation of the Alox15 gene protected female mice from DSS-induced colitis, transgenic overexpression of human ALOX15 did hardly impact the intensity of the inflammatory symptoms." (PMID 37498393, 2023). "Alox15 deletion has been reported to promote inflammation suppression, intestinal barrier integrity maintenance, and colonic injury, while Alox15 overexpression exhibits more severe symptoms of colitis." (PMID 35378823, 2022).
colitis (continued). "In other words, in DSS colitis the first effect of our genetic manipulation (prevention of endogenous leukotriene biosynthesis) is likely to induce less severe colitis symptoms but this protective effect might be compensated by the augmented formation of Alox15 products by the mutant enzyme." (PMID 34677413, 2021). "More specifically, the levels of Alox5 and Alox15 are upregulated in the colonic mucosa in patients with IBD and in the experimental colitis mouse model, respectively." (PMID 34733403, 2021). "Moreover, the 15-LOX metabolite 15-HEPE was also reduced in ALOX15-silenced fat1 transgenic mice, and the wild-type mice were protected against the development of DSS-induced colitis after intraperitoneal injections with 15-HEPE." (PMID 38675565, 2024). "Taken together, these data suggest that transgenic expression of human ALOX15 under the control of the aP2 promoter does not protect from DSS-induced colitis as it was the case in the FCA paw edema model." (PMID 37498393, 2023). "For Alox15-KI mice similar kinetics were observed but we did not detect significant differences between the two genotypes at either time point of the experimental colitis." (PMID 40653455, 2025). "Transgenic aP2-ALOX15 mice were tested in comparison with Alox15 knockout mice (Alox15−/−) and corresponding wildtype control animals (C57BL/6J) in the complete Freund’s adjuvant induced hind-paw edema model and in the dextran sulfate sodium induced colitis (DSS-colitis) model." (PMID 37498393, 2023). "Interestingly, expression of Alox15 was not seen in healthy mouse colon but was significantly upregulated in the inflamed colon after 8 days of DSS induced colitis." (PMID 34064822, 2021).
Obesity (14 papers, 2016 to 2025). Accumulation of substantial excess body fat. "Interestingly, ALOX15 activity has also been linked to obesity as the enzyme is highly expressed in omental tissue compared to the subcutaneous fat layer of obese patients." (PMID 30282920, 2018). "ALOX15−/− mice are resistant to the induction of type-1 diabetes and also to the inflammatory effects of obesity induced by a Western-type diet." (PMID 36902243, 2023). "There is current information on the genetic modulation of ALOX5 and ALOX15 expression during obesity, where ALOX5 promotes leukotrienes, lipoxins, and resolvins production." (PMID 38024342, 2023). "Accordingly, analysis of ALOX15 transgenic mice supports a link between inflammation, obesity and insulin resistance." (PMID 30282920, 2018). "With these lines of evidence, the activity of ALOX15 may have a systemic and indirect effect on male infertility through obesity, alongside the direct effects it may have within the male germline through 4HNE production." (PMID 30282920, 2018). "Although the underlying mechanism is unknown, the results suggest an interaction between Alox15 expression in adipose tissue and islet inflammation, and inhibition of Alox15 expression in adipose tissue may provide systemic protection against obesity-induced consequences." (PMID 37849828, 2023). "The arachidonate 12-lipoxygenase (ALOX12) and arachidonate 15-lipoxygenase (ALOX15) genes have been shown to be connected to obesity phenotypes and possess the capacity to treat obesity (e.g., inflammation and IR)." (PMID 39080624, 2024). "Gene expression of key enzymes involved in eicosanoid production was reduced (COX1, HPGDS, LPGDS, ALOX15, all p ≤ 0.05) or unaltered (COX2, ALOX5) during critical illness, irrespective of obesity." (PMID 28303483, 2017).
nasal polyps (10 papers, 2017 to 2025). "The expression of ALOX15 is higher in eosinophilic nasal polyps, and a missense variant in ALOX15 protects against nasal polyps." (PMID 35095530, 2021). "The correlation between Alox15 and inflammation‐related genes was also established in chronic rhinosinusitis with nasal polyps." (PMID 40389328, 2025). "Alox15+ macrophages contributed to type 2 immunity in eosinophilic chronic rhinosinusitis with nasal polyps, while inhibition of Alox15 alleviated type 2 inflammation." (PMID 40389328, 2025). "We also identified protective variants such as APP p.Ala673Thr (rs63750847, P = 7 × 10−11) reducing odds of developing AD, and ALOX15 p.Thr560Met protecting against nasal polyps (rs34210653, P = 2 × 10−15)." (PMID 39563277, 2024). "It has also been reported that PD146176 can reduce the epithelial-mesenchymal transition (EMT) in eosinophilic chronic rhinosinusitis (ECRS) with nasal polyps after inhibiting ALOX15 expression." (PMID 37849828, 2023).
Sepsis (10 papers, 2021 to 2026). Sepsis is defined as life-threatening organ dysfunction caused by a dysregulated host response to infection. "We found that relative to uninfected controls, human neonates with clinical sepsis exhibited significantly reduced expression of ALOX15, PTGS2 and CYP2J2, implicating all main AA metabolic pathways in sepsis." (PMID 38769383, 2024). "Except for CYP4V2, there were also three genes down-regulated in sepsis, including ALOX15, BCL2, and FTO." (PMID 36820206, 2023). "Moreover, there is emerging research that suggests ALOX15 therapeutic activation and bioregulation are compelling targets for treating sepsis, airway pathology, and systemic inflammation in patients." (PMID 39346910, 2024). "Additionally, studies of mice undergoing remnant nephrectomy, diabetic nephropathy, and sepsis-induced acute kidney injury had a similar profibrotic role of ALOX15." (PMID 36864028, 2023). "Innate immunity and inflammation, such as ZDHCC19, ALOX15, FCER1A, HDC, PRSS33, and PCSK9, were upregulated in elderly ICU patients with sepsis." (PMID 36823620, 2023). "On day-8 in elderly ICU patients with sepsis, genes related to innate immunity and inflammation, such as ZDHCC19, ALOX15, FCER1A, HDC, PRSS33, and PCSK9, were upregulated." (PMID 36823620, 2023).
lung carcinoma (9 papers, 2017 to 2024). "A recent review highlighted the importance of ALOX15 in the formation of key lipid mediators to terminate inflammation during lung cancer in humans." (PMID 38900131, 2024). "In particular, ALOX15 has long been regarded as a critical mediator and thus a prominent indicator in the seton session of lung cancer." (PMID 34434214, 2021). "Mounting evidence indicates that ALOX15 is down-regulated in many human cancers, including colorectal, prostate, breast (Jiang, Douglas-Jones & Mansel, 2003) and lung cancers." (PMID 34434660, 2021).
Arthritis (8 papers, 2019 to 2025). Inflammation of a joint. "In two different arthritis models systemic functional inactivation of the Alox15 gene induced uncontrolled inflammation and tissue damage and these data suggested an anti-inflammatory function of Alox15." (PMID 40653455, 2025). "We found the expression of Alox15 (12/15-LO gene) peaked around 4-weeks post-infection in C3H mice suggesting a role for 12/15-LO in mediating arthritis resolution." (PMID 37143678, 2023). "For example, mice with ALOX15, an isoform of ALOX8, knocked out had arthritis, with increased levels of IL-6 and IL-1β as compared with their wild-type controls, and the level of KC was correlated to their body weight loss." (PMID 31013822, 2019).
pancreatic cancer (8 papers, 2017 to 2024). "In pancreatic cancer, ALOX15 is known to be lost in islets and pancreatic intraepithelial lesions but strongly expressed in normal acinar and ductal cells." (PMID 38612771, 2024). "Findings from other research works show that overexpression of ALOX15 in pancreatic cancer cells and inhibition of ALOX5 and platelet-type 12-lipoxygenase exert anti-tumorigenic effects." (PMID 38612771, 2024). "For instance, ALOX15 can catalyze lipid hydroperoxide generation and ferroptosis in pancreatic cancer, while mitochondrial-targeted nitroxide holds the ability to prevent mitochondrial lipid oxidation on the contrary." (PMID 34631790, 2021). "Another study showed that ALOX15 silencing protected ferroptosis induced by erastin and RSL3 in oncogenic Ras-expressing cancer cells including HT1080 (human fibrosarcoma cell), PANC-1 (human pancreatic carcinoma cell) and CALU-1 (human non-small lung cancer)." (PMID 35721535, 2022).
Alzheimer disease (6 papers, 2014 to 2025). A progressive, neurodegenerative disease characterized by loss of function and death of nerve cells in several areas of the brain leading to loss of cognitive function such as memory and language. "The ALX/FPR2 receptor and 15-LOX (ALOX15) are expressed in the hippocampus of patients with Alzheimer’s disease suggesting that resolution mechanisms might be active in human CNS diseases with a pathogenic neuroinflammatory component." (PMID 30307467, 2018).
Hepatic steatosis (6 papers, 2017 to 2025). Steatosis is a term used to denote lipid accumulation within hepatocytes. "Studies on fatty liver disease in Alox15-knockout mice showed decreased liver fat, highlighting the possibility of neutral lipid derangements in our HMD phenotype." (PMID 39436697, 2024). "ALOX15 deletion in hyperlipidemic ApoE knockout mice improved hepatic steatosis, liver inflammation, and insulin resistance." (PMID 38071367, 2023). "In one study, whole-body Alox15−/− mice were protected from hepatic steatosis under conditions of high-fat diet feeding." (PMID 34064822, 2021). "Our findings suggest that inhibiting ALOX15 in the liver may be beneficial in treating age-related liver steatosis." (PMID 38071367, 2023). "Some studies have reported that Alox15 deficiency, which lowers plasma 15-HETE levels, protects against steatohepatitis, hyperlipidemia, and alcoholic liver disease by reducing reactive oxygen species production, hepatic steatosis, insulin resistance, and inflammatory injury." (PMID 40356654, 2025). "A study of whole‐body Alox15−/− mice under a HFD revealed a decrease in lymphocyte infiltration and pro‐inflammatory mRNA levels of TNFα and IFN‐γ, thereby protecting against hepatic steatosis." (PMID 36637998, 2023).
ischemia (6 papers, 2016 to 2025). A hypoperfusion of the BLOOD through an organ or tissue caused by a PATHOLOGIC CONSTRICTION or obstruction of its BLOOD VESSELS, or an absence of BLOOD CIRCULATION. "The induction of ALOX15 was identified as a determinant of susceptible factor in PUFAs-induced ischemia." (PMID 35970840, 2022). "After ischemia, ALOX15 levels increase in neurons and ECs; ALOX15 can directly oxidize lipid membranes containing PUFAs." (PMID 41427019, 2025). "In this respect, our finding on the role of ALOX15 as a potential therapeutic target of ischemia injury led to identification of daidzein as a potent ALOX15 inhibitor, which shows promise in the treatment for both phases of I/R injury." (PMID 35970840, 2022). "As expected, LAD ligation-induced ischemia increased gene and protein levels of ALOX15, and HFD augmented this change." (PMID 35970840, 2022). "Using PUFA-enriched cells and animals we show that the lipoxygenase, arachidonic acid 15-lipoxygenase-1 (ALOX15) initiates specific redox reactions in PUFA-phospholipids, which increases susceptibility to ischemia injury." (PMID 35970840, 2022). "The insensitivity of Alox15–/– mice to ischemia was related to phospholipid peroxidation as inferred by the observation that in rat ischemia induced by LAD." (PMID 35970840, 2022). "Using multi-omics, arachidonic acid 15-lipoxygenase-1 (ALOX15) was identified as the primary mediator of ischemia-provoked phospholipid peroxidation, which was further confirmed using chemogenetic approaches." (PMID 35970840, 2022). "Next, leading-edge genes enriched in metabolism-related pathways between sham and ischemia hearts were examined to reveal that ALOX15, a core enzyme in phospholipid peroxidation and ferroptosis was greatly upregulated at the gene expression and protein levels under ischemia conditions." (PMID 35970840, 2022). "To investigate whether ischemia affects ALOX15 expression in cardiac endothelial cells, we incubated human cardiac endothelial cells in normoxic or hypoxic conditions for 6 h." (PMID 27552229, 2016).
myocardial infarction (6 papers, 2013 to 2025). Gross necrosis of the myocardium, as a result of interruption of the blood supply to the area, as in coronary thrombosis. "Alox15 deficiency reduced the size of the myocardial infarcts; inhibited cardiac fibrosis; decreased lipid peroxidation products." (PMID 37942067, 2023). "In myocardial infarction, inhibition of ALOX15 was able to limit ferroptosis and lipid peroxidation while simultaneously elevating GSH levels in the PUFA-enriched cells." (PMID 40622464, 2025). "None of the ALOX15 polymorphisms has been associated with myocardial infarction, but the rare ALOX15 haplotype has shown a significant protective effect on the risk of myocardial infarction." (PMID 36011386, 2022). "However, future studies are required to determine whether the increased 15-HETE production in ischemic heart tissue contributes to thrombosis and the potential for ALOX15 as a therapeutic target for myocardial infarction." (PMID 27552229, 2016). "Knockdown of ENST00000538705.1 or ALOX15 reduces myocardial damage, decreases serum total cholesterol and LDL levels, and increases HDL levels in rats with myocardial infarction." (PMID 36011386, 2022). "Myocardial infarction rat models were established and administrated with siRNAs against ENST00000538705.1 or ALOX15." (PMID 35571613, 2022). "Additionally, knockdown of ENST00000538705.1 or ALOX15 relieved myocardial damage, decreased serum TC and LDL levels, and elevated HDL levels in myocardial infarction rats." (PMID 35571613, 2022).
neuroblastoma (5 papers, 2012 to 2023). Neuroblastoma (NB) is the most common solid, extracranial childhood tumor. "In this study, we elucidate epigenetic regulation of Alox15 in SH-SY5Y human neuroblastoma cells using HDAC and HAT inhibitors." (PMID 29235036, 2018). "Together, results indicate regulation of Alox15 mRNA expression in neuroblastoma cells by histone modifications, and increasing Alox15 expression in differentiating neurons." (PMID 29235036, 2018). "Treatment of undifferentiated SH-SY5Y human neuroblastoma cells with the histone deacetylase (HDAC) inhibitors trichostatin A (TSA) and sodium butyrate significantly increased Alox15 mRNA expression." (PMID 29235036, 2018). "Together, results indicate regulation of Alox15 mRNA expression in neuroblastoma cells by HDACs and HAT, and increasing levels of Alox15 expression with differentiation." (PMID 29235036, 2018).